ADCY7 (adenylate cyclase 7)
Description:
Adenylate cyclase that mediates formation of both cyclic AMP (cAMP) and cyclic di-AMP (c-di-AMP). Acts as a key mediator of G protein-coupled receptor signaling by catalyzing the formation of cAMP downstream of G protein-coupled receptors. Functions in G protein-coupled receptor signaling cascades activated by thrombin, sphingosine 1-phosphate, dopamine and anaphylatoxin C5a. Mediates regulation of cAMP synthesis through synergistic action of the G alpha protein G(s) (GNAS) with G(13) (GNA13). Also involved in inflammation by acting as a diadenylate cyclase that catalyzes the condensation of 2 ATP molecules into c-di-AMP (By similarity). Following activation by TLR9, mediates formation of c-di-AMP, which directly activates NLRP3, thereby promoting assembly and maturation of the NLRP3 inflammasome (By similarity). It is also required for the optimal functions of B- and T cells during adaptive immune responses by regulating cAMP synthesis in both B- and T-cells (By similarity).
Synonyms: KIAA0037; AC7
Tractability: Antibody: its Gene Ontology location is reachable by antibodies, with high confidence; UniProt predicts a signal peptide or a membrane-spanning region; the Human Protein Atlas places it where antibodies can reach. PROTAC: ubiquitination databases record sites on it; its protein half-life has been measured; a small molecule that binds it is known.
Gene: Protein-coding gene on chromosome 16 (50,246,137 to 50,318,135, forward strand). Ensembl gene ENSG00000121281.
Subcellular location: Membrane
Subcellular location (Human Protein Atlas): Plasma membrane; Rods & Rings; Vesicles
Pathways (Reactome):
Signal Transduction: Adenylate cyclase activating pathway; G alpha (i) signalling events; G alpha (s) signalling events; G alpha (z) signalling events; GPER1 signaling; Hedgehog 'off' state; PKA activation
Disease: ADORA2B mediated anti-inflammatory cytokines production; FCGR3A-mediated IL10 synthesis
Metabolism: Glucagon signaling in metabolic regulation; PKA activation in glucagon signalling
Cellular responses to stimuli: High laminar flow shear stress activates signaling by PIEZO1 and PECAM1:CDH5:KDR in endothelial cells
Neuronal System: Adenylate cyclase inhibitory pathway
Transport of small molecules: Vasopressin regulates renal water homeostasis via Aquaporins
Gene Ontology:
Molecular function: adenylate cyclase activity; diadenylate cyclase activity; phosphorus-oxygen lyase activity
Biological process: cAMP biosynthetic process; cellular response to ethanol; adenylate cyclase-activating G protein-coupled receptor signaling pathway; cellular response to glucagon stimulus; cellular response to lithium ion; negative regulation of cytokine production involved in inflammatory response; positive regulation of NLRP3 inflammasome complex assembly; positive regulation of toll-like receptor 9 signaling pathway; regulation of adaptive immune response; renal water homeostasis; vascular endothelial cell response to laminar fluid shear stress; cyclic nucleotide biosynthetic process; intracellular signal transduction; maternal process involved in female pregnancy
Cellular component: membrane; plasma membrane
Genetic constraint (gnomAD): Loss-of-function variants: 70 observed, 115.67 expected, observed/expected ratio (o/e) 0.61, 90% interval 0.5 to 0.74. The upper end of that interval is the gene's LOEUF score, 0.74, which puts it in group 3 of 6, group 1 being the genes least tolerant of losing a copy. Missense variants: 1,191 observed, 1,439.7 expected, observed/expected ratio (o/e) 0.83, 90% interval 0.79 to 0.87. Synonymous variants: 644 observed, 614.52 expected, observed/expected ratio (o/e) 1.05, 90% interval 0.98 to 1.12.
Homologues: Orthologues: chimpanzee ADCY7 (99% identical), macaque ADCY7 (97% identical), pig ADCY7 (89% identical), rabbit ADCY7 (89% identical), dog ADCY7 (87% identical), guinea pig ADCY7 (86% identical), rat Adcy7 (84% identical), mouse Adcy7 (84% identical), tropical clawed frog adcy7 (62% identical), zebrafish adcy7 (56% identical). Paralogues in human: ADCY2 (55% identical), ADCY4 (52% identical), ADCY5 (37% identical), ADCY6 (37% identical), ADCY1 (35% identical), ADCY3 (34% identical), ADCY8 (33% identical), ADCY9 (27% identical), GUCY2D (16% identical), GUCY2F (16% identical), NPR1 (15% identical), NPR2 (15% identical), and 5 more.
Diseases named in the same sentence as ADCY7 in open-access papers:
ADCY7 is named in the same sentence as 45 diseases in open-access papers, as found by Europe PMC text mining. Sharing a sentence is not in itself a finding about the gene and the disease. The quoted sentences say what the papers report.
acute myeloid leukemia (4 papers, 2018 to 2023). Acute myeloid leukemia (AML) is a group of neoplasms arising from precursor cells committed to the myeloid cell-line differentiation. "The literature has demonstrated that ADCY7 and the prognosis of acute myeloid leukemia are closely related, and its high expression may be detrimental to the prognosis of patients with this disease." (PMID 36110123, 2022). "Studies have shown that ADCY7 expression is significantly negatively correlated with overall survival in patients with acute myeloid leukemia and that ADCY7 can promote the progression of acute myeloid leukemia by promoting tumor cell proliferation and migration." (PMID 36979847, 2023).
depression (4 papers, 2022 to 2023). "Postmortem study found increased ADCY7 expression in the amygdala and anterior cingulate cortex of patients with depression." (PMID 35307032, 2022). "There is also evidence suggesting that ADCY7 is involved in mood regulation and major depressive disorder." (PMID 35307032, 2022). "The same study also examined polymorphisms in ADCY7, specifically a variable tetranucleotide (AACA) repeat, in the 3’ UTR of human populations in relation to depression." (PMID 36467104, 2022). "It has been reported that overexpression of ADCY7 in female mice increases depression-like behaviors, while ADCY7+/− mice display decreased depression-like symptoms." (PMID 35307032, 2022).
alcohol dependence (2 papers, 2011 to 2022). Physical and psychological dependence on alcohol. "To demonstrate relevance of this gene for alcohol dependence in humans, we tested the association of polymorphisms in the ADCY7 gene with alcohol dependence in a sample of 1703 alcohol-dependent individuals and 1347 control subjects." (PMID 21481845, 2011). "The SNP most associated with alcohol dependence (rs2302717) is located in intron five of the ADCY7 gene and is in high LD with several markers at the 5′ region of the ADCY7 gene." (PMID 21481845, 2011). "In the human sample, we found that single nucleotide polymorphisms in ADCY7 associate with alcohol dependence in women, and these markers are also associated with ADCY7 expression (messenger RNA) levels." (PMID 21481845, 2011). "Our expression quantitative trait loci analyses indicate that the marker most associated with alcohol dependence in our study (rs2302717) and/or other SNPs in LD (like rs1078151) affects ADCY7 expression." (PMID 21481845, 2011). "Although behavioral experiments using genetically modified mice demonstrate a sex-specific role for this gene in voluntary alcohol consumption, the human genetic study identifies a genetic polymorphism within the ADCY7 gene associating with alcohol dependence in human female subjects." (PMID 21481845, 2011). "Our findings provide the first evidence for a role for ADCY7 in development of alcohol dependence in women." (PMID 21481845, 2011).
epilepsy (2 papers, 2021 to 2025). A brain disorder characterized by episodes of abnormally increased neuronal discharge resulting in transient episodes of sensory or motor neurological dysfunction, or psychic dysfunction. "As the localization of AC7 was observed in the hippocampus, cerebral cortex, cerebellum, caudate-putamen, and nucleus accumbens, ADCY7 involving in regulation of GABA may be correlated with epilepsy." (PMID 34555062, 2021).
hypothyroidism (2 papers, 2020 to 2025). Abnormally low levels of thyroid hormone. "For example, the missense variant rs78534766 in ADCY7 and the FLT3 variant rs76428106 associated with large effects on hypothyroidism (OR = 1.4 and 1.37, respectively) but had a comparably small effect on TSH levels (s.d. = 0.04 and 0.08, respectively)." (PMID 41238958, 2025).
Anxiety (1 paper, 2013). Intense feelings of nervousness, tension, or panic often arise in response to interpersonal stresses. "Here, we also report that XY- mice have lower expression of Adcy7 compared to XX mice and a negative correlation between Adcy7 expression and anxiety-like behavior in gonadal females." (PMID 24199867, 2013).
autism spectrum disorder (1 paper, 2022). A spectrum of developmental disorders that includes autism, and Asperger syndrome. "De novo mutations in ADCY7 have been reported in autism spectrum disorders (ASD) where the gene has been proposed to be a risk factor." (PMID 36232428, 2022).
cervical cancer (1 paper, 2023). A primary or metastatic malignant neoplasm involving the cervix. "In cervical cancer, ADCY7 mRNA levels are associated with immune cell infiltration levels using TIMER platforms." (PMID 36979847, 2023). "This study indicates that targeting ADCY7 can serve as a new direction for immunotherapy for cervical cancer and further block HR-HPV persistent infections." (PMID 36979847, 2023). "Based on the TCGA-CESC data sets, a Kaplan–Meier survival analysis was conducted to investigate the role of ADCY7 mRNA levels in cervical cancer survival." (PMID 36979847, 2023). "However, there are few studies about ADCY7 expression status and its biological function in cervical cancer." (PMID 36979847, 2023). "Moreover, higher ADCY7 expression levels predict a poor prognosis in cervical cancer due to the promotion of the expression of the immune checkpoint." (PMID 36979847, 2023). "Therefore, this study further demonstrates that ADCY7 can be used as a new target for cervical cancer treatment." (PMID 36979847, 2023). "Higher ADCY7 mRNA levels predict a poor prognosis in cervical cancer." (PMID 36979847, 2023). "Moreover, this study indicated that higher ADCY7 levels could be a suitable predictor for poor prognosis in cervical cancer due to immune cell infiltration." (PMID 36979847, 2023). "This study fills the gaps in the primary and clinical research of the ADCY7 protein in the field of cervical cancer; provides theoretical support for the prevention, diagnosis, and treatment of cervical cancer; and seeks new targets for the treatment of cervical cancer." (PMID 36979847, 2023). "The results provide novel insights into the active role of ADCY7 in HPV infection and cervical cancer, thereby highlighting a potential mechanistic basis whereby ADCY7 influences immune cell interactions with tumors." (PMID 36979847, 2023). "However, there are some limitations, as follows: Firstly, we did not verify the relationship between ADCY7 expression levels and the prognosis of cervical cancer based on our clinical data in this study, which is worth further study." (PMID 36979847, 2023).
cervical intraepithelial neoplasia (1 paper, 2023). "The relationship between ADCY7 and cervical intraepithelial neoplasia in grade 2 and higher (CIN2+) was analyzed, and the optimal cut-off values of the relative expression of ADCY7 mRNA to predict CIN2+ were calculated." (PMID 36979847, 2023).
gastric cancer (1 paper, 2013). A primary or metastatic malignant neoplasm involving the stomach. "Different levels of ADCY7 and ADCY9 were detected in gastric cancer and normal cell lines." (PMID 24113161, 2013).
Hypoglycemia (1 paper, 2021). A decreased concentration of glucose in the blood. "However, the exact mechanism by which ADCY7 leads to excessive insulin secretion through GSIS is still not explained by only increasing SLC2A2 and GCK expression during hypoglycemia conditions." (PMID 34177802, 2021).
pregnancy disorder (1 paper, 2017). A disorder that is related to pregnancy. "Finally, we also identified five genes (PLCB1, LUM, ADCY7, IRF7, and EHHADH) that we predict to be important for pregnancy disorders and placenta development, although such links remains to be established." (PMID 29222466, 2017).
renal carcinoma (1 paper, 2021). A carcinoma arising from the epithelium of the renal parenchyma or the renal pelvis. "ADCY7 plays a role in the CXCR4 pathway, and its deficiency has been found in patients with renal cancer-related muscle atrophy." (PMID 34688260, 2021).
Renal cyst (1 paper, 2011). A fluid filled sac in the kidney. "We observed up-regulation of adenylyl cyclase, Adcy7, which may increase cAMP production in the renal cysts, which in turn promotes renal cystic epithelial proliferation in PKD." (PMID 21518438, 2011).
cancer (10 papers, 2010 to 2025). A tumor composed of atypical neoplastic, often pleomorphic cells that invade other tissues. "Recently, some research pointed out that adenylate cyclase 7 (ADCY7) is abnormally expressed in a variety of human cancers and is associated with mismatch repair (MMR) gene expression and DNA methyltransferase (DNMT) expression." (PMID 36979847, 2023). "By contrast, ADCY1 expression did not affect the prognosis of AML patients, suggesting the actions of group 2 adenylyl cyclases (ADCY2, ADCY4 and ADCY7) in AML differ from those in other cancers." (PMID 32568101, 2020). "The comparison of mRNA levels of ADCY6 and ADCY7 in normoxic versus hypoxic samples revealed their increased hypoxic transcription in all four cancer cell types, whereas ADCY3 was unchanged or reduced." (PMID 28860539, 2017). "Both KCNK9 and ADCY7 are often found overexpressed in human cancers." (PMID 37958378, 2023). "Subsequently, we identified five genetic variants in known cancer-related genes (located within SIPA1, ADCY7 and ARNT2) that could be associated with cancer mortality residuals corrected for confounding factors." (PMID 32661568, 2020). "We found that ADCY7 mRNA levels were strongly correlated with the infiltrating degree of CD4+ T cells, T cells gamma delta, macrophages, neutrophils, M1 macrophages, myeloid dendritic cells, mast cells, endothelial cells, cancer-association fibroblasts, and NK cells." (PMID 36979847, 2023). "Again, annotation to OMIM revealed that several cancer-related genes were involved in these LOH regions (MLH1, ZMAT3, ADCY7, PIK3CA)." (PMID 20428235, 2010). "It appears that the interactomes of five out of the 17 lithium-sensitive genes (ADCY2, ADCY5, ADCY7, BPNT1, and HIPK3) do not show significant mutual enrichment with the cancer pathways explored in this study." (PMID 31114752, 2019).
tumour (5 papers, 2017 to 2023). "Both PECAM1 and ADCY7 promoted tumor progression through the AKT pathway, showing the same molecular mechanism as CD300A." (PMID 29938007, 2018). "Both PECAM1 and ADCY7 promote tumor progression through the AKT pathway, showing the same molecular mechanism as CD300A." (PMID 29938007, 2018). "This evidence suggests that targeting ADCY7 may enhance the anti-tumor effect by increasing the infiltration of anti-tumor immune cells and promoting the expression of the immune checkpoint." (PMID 36979847, 2023). "To summarize, we, for the first time, confirmed that CD300A promoted tumor progression by increase PECAM1 and ADCY7 expression, and activating the AKT/mTOR signaling pathway in AML." (PMID 29938007, 2018). "In briefly, CD300A may contribute to tumor proliferation and apoptosis by upregulating PECAM1 and ADCY7, in addition to recruiting PTP in AML cells." (PMID 29938007, 2018). "However, it is interesting to note that CD300A inhibits the apoptosis through PECAM1 but not ADCY7 in U937 cells, implying the unknown mechanisms by which CD300A promotes tumor progression." (PMID 29938007, 2018).
bacterial infections (1 paper, 2022). "Loss of ADCY7 leads to fewer leukocytes and higher mortality upon bacterial infections, indicating an essential role of ADCY7 in immune responses." (PMID 35307032, 2022).
nervous system diseases (1 paper, 2025). "Adenylate cyclase 7 (ADCY7) plays a critical role in nervous system diseases, inflammatory responses, and immune responses, and ADCY7 was abnormally expressed in multiple cancers and may be a prognostic biomarker of tumorigenesis." (PMID 40761790, 2025).
ADCY7 also shares sentences with these, for which no sentence is quoted: alcoholism (2 papers); autoimmune conditions (2); leukemia (2); ovarian carcinoma (2); acute promyelocytic leukemia (1); alcohol use disorder (1); autoimmune thyroid disease (1); cervical (1); cutaneous squamous cell carcinoma (1); developmental delays (1); dilated cardiomyopathy (1); heart failure (1); hepatocellular carcinoma (1); Hypercholesterolemia (1); Hypertension (1); infection (1); inflammatory bowel disease (1); intellectual disabilities (1); leprosy (1); lymphoma (1); Marfan syndrome (1); neurodegenerative disease (1); overgrowth syndrome (1); Parkinson disease (1); schizophrenia (1); Sepsis (1); type 2 diabetes mellitus (1).